CHMP4A (charged multivesicular body protein 4A)
Description:
Probable core component of the endosomal sorting required for transport complex III (ESCRT-III) which is involved in multivesicular bodies (MVBs) formation and sorting of endosomal cargo proteins into MVBs. MVBs contain intraluminal vesicles (ILVs) that are generated by invagination and scission from the limiting membrane of the endosome and mostly are delivered to lysosomes enabling degradation of membrane proteins, such as stimulated growth factor receptors, lysosomal enzymes and lipids. The MVB pathway appears to require the sequential function of ESCRT-O, -I,-II and -III complexes. ESCRT-III proteins mostly dissociate from the invaginating membrane before the ILV is released. The ESCRT machinery also functions in topologically equivalent membrane fission events, such as the terminal stages of cytokinesis and the budding of enveloped viruses (HIV-1 and other lentiviruses). ESCRT-III proteins are believed to mediate the necessary vesicle extrusion and/or membrane fission activities, possibly in conjunction with the AAA ATPase VPS4. When overexpressed, membrane-assembled circular arrays of CHMP4A filaments can promote or stabilize negative curvature and outward budding. Via its interaction with PDCD6IP involved in HIV-1 p6- and p9-dependent virus release. CHMP4A/B/C are required for the exosomal release of SDCBP, CD63 and syndecan.
Synonyms: Vps32-1; C14orf123; SHAX2; HSPC134; VPS32A; hSnf7-1; Snf7-1; CHMP4; SNF7
Tractability: Antibody: UniProt places it where antibodies can reach, with high confidence; its Gene Ontology location is reachable by antibodies, with high confidence. PROTAC: ubiquitination databases record sites on it; its protein half-life has been measured.
Gene: Protein-coding gene on chromosome 14 (24,209,615 to 24,213,830, reverse strand). Ensembl gene ENSG00000254505.
Subcellular location: Cytoplasmic vesicle membrane; Late endosome membrane
Pathways (Reactome):
Disease: Budding and maturation of HIV virion; HCMV Late Events; Translation of Replicase and Assembly of the Replication Transcription Complex
Autophagy: Late endosomal microautophagy; Macroautophagy
Cell Cycle: Sealing of the nuclear envelope (NE) by ESCRT-III
Programmed Cell Death: Pyroptosis
Vesicle-mediated transport: Endosomal Sorting Complex Required For Transport (ESCRT)
Gene Ontology:
Molecular function: ATPase binding; identical protein binding; protein binding; protein homodimerization activity
Biological process: autophagosome maturation; autophagy; late endosome to lysosome transport; membrane invagination; midbody abscission; mitotic metaphase chromosome alignment; multivesicular body sorting pathway; nervous system process; nuclear membrane reassembly; nucleus organization; plasma membrane repair; plasma membrane tubulation; post-translational protein targeting to endoplasmic reticulum membrane; protein polymerization; regulation of mitotic spindle assembly; ubiquitin-dependent protein catabolic process via the multivesicular body sorting pathway; vesicle budding from membrane; viral budding from plasma membrane; viral budding via host ESCRT complex; late endosome to vacuole transport via multivesicular body sorting pathway; macroautophagy; membrane fission; multivesicular body assembly; multivesicular body-lysosome fusion; vesicle fusion with vacuole; and 1 more
Cellular component: amphisome membrane; autophagosome membrane; cytoplasm; cytoplasmic side of plasma membrane; endosome; ESCRT III complex; kinetochore; kinetochore microtubule; lysosomal membrane; membrane coat; midbody; multivesicular body membrane; nuclear pore; nucleus; plasma membrane; cytosol; nuclear envelope; cytoplasmic vesicle membrane; late endosome membrane
Genetic constraint (gnomAD): Loss-of-function variants: 28 observed, 28.58 expected, observed/expected ratio (o/e) 0.98, 90% interval 0.73 to 1.34. The upper end of that interval is the gene's LOEUF score, 1.34, which puts it in group 5 of 6, group 1 being the genes least tolerant of losing a copy. Missense variants: 241 observed, 276.45 expected, observed/expected ratio (o/e) 0.87, 90% interval 0.78 to 0.97. Synonymous variants: 88 observed, 105.12 expected, observed/expected ratio (o/e) 0.84, 90% interval 0.7 to 1.
Homologues: Orthologues: rabbit CHMP4A (93% identical), pig CHMP4A (93% identical), dog CHMP4A (91% identical). Paralogues in human: CHMP4B (63% identical), CHMP4C (57% identical), CHMP4BP1 (48% identical), CHMP5 (30% identical), CHMP7 (24% identical).
Diseases named in the same sentence as CHMP4A in open-access papers:
CHMP4A is named in the same sentence as 16 diseases in open-access papers, as found by Europe PMC text mining. Sharing a sentence is not in itself a finding about the gene and the disease. The quoted sentences say what the papers report.
ovarian carcinoma (4 papers, 2014 to 2025). A malignant neoplasm originating from the surface ovarian epithelium. "Microarray analysis demonstrated that CHMP4A was used as a prognostic biomarker and druggable target for various diseases such as hepatocellular carcinoma, colorectal cancer, and ovarian carcinoma." (PMID 40909968, 2025). "Some research based on microarray analysis has demonstrated that CHMP4A could act as prognostic biomarkers and druggable targets for various diseases, including hepatocellular carcinoma, colorectal cancer, and ovarian carcinoma." (PMID 37168851, 2023). "It has been reported that the level of CHMP4A was markedly increased in men with high GS prostate cancer, and in patients with advanced high-grade serious ovarian cancer (HGSOC), and thereby it could act as a potential biomarker for cancers." (PMID 36267972, 2022). "Similarly, three other genes, namely, CYP4B1, CEPT1, and CHMP4A are differentially regulated in patients who suffer from recurrent ovarian cancer disease." (PMID 27382614, 2014). "Another recent study integrated TCGA data and validated three genes (CYP4B1, CEPT1, and CHMP4A) in HGS-OvCa from patients likely to be cured by initial cytoreductive surgery and adjuvant chemotherapy; the precise role of these genes in ovarian cancer pathophysiology remains to be elucidated." (PMID 27382614, 2014).
virus infection (4 papers, 2021 to 2023). "Some studies demonstrated that CHMP4A promotes mitotic cytokinetic, midbody abscission and multivesicular body organization, which play the functional role in involving viral infection partly related to the significance of ESCRT-III in the HCC progression." (PMID 36267972, 2022). "The ESCRT, complex, ALIX-CHMP4A, is recruited to NS3 through their interactions with the putative L domain motif of NS3, while CHMP4A is recruited to E. In addition, we demonstrate the antiviral mechanism of ISG15 and HERC5, which degrades ALIX and CHIMP4A, indirectly targets virus infection." (PMID 34851141, 2022).
Flavivirus Infections (3 papers, 2022 to 2024). Infections with viruses of the genus FLAVIVIRUS, family FLAVIVIRIDAE. "Additionally, ALIX and charged multivesicular body protein 4A (CHMP4A) are required during flavivirus infection, though detailed mechanisms remain to be fully elucidated." (PMID 39337546, 2024). "By siRNA-mediated gene silencing, we showed that ALIX and CHMP4A, two members of the host endosomal sorting complex required for transport (ESCRT) protein machinery, are required during flavivirus infection." (PMID 34851141, 2022).
prostate carcinoma (3 papers, 2017 to 2023). A carcinoma that arises from epithelial cells of the prostate gland. "Granulin, AMBP, CHMP4A, and CHMP4C were also higher in men with high GS prostate cancer (p-value < 0.05)." (PMID 28211531, 2017). "Among them, fatty acid binding protein 5 (FABP5), Alpha-1-Microglobulin/Bikunin Precursor (AMBP), Charged Multivesicular Body Protein 4A (CHMP4A), and Charged Multivesicular Body Protein 4C (CHMP4C) were significantly differentially expressed in prostate cancer patients compared to normal samples." (PMID 38201450, 2023). "GRN, AMBP, CHMP4A, CHMP4C, and CHMP2 may play important roles in aggressive prostate cancer and may be potential targets of treatment." (PMID 28211531, 2017).
melanoma (2 papers, 2023 to 2025). A malignant, usually aggressive tumor composed of atypical, neoplastic melanocytes. "In combination, the findings suggested that GZMA, GSDMB, NLRP1, CHMP4A, and IL18 deficiency, at least in part, are responsible for melanoma." (PMID 37620327, 2023). "Very little was found in the literature on the question of CHMP4A in melanoma, which needs further research." (PMID 37620327, 2023). "CHMP4A revealed low expression in melanoma as a prognostic gene in our study." (PMID 40909968, 2025). "In GSE46517, IFFO1, ANKRD10, CLPB, TCAP, and POLG2 displayed high expression, but the expression levels of CHMP4A, ZDHHC11, and ANKMY1 were low in the melanoma group." (PMID 40909968, 2025). "Histologically, melanoma tissues had fewer positive cells percentage of PRGs, GZMA, GSDMB, NLRP1, IL18, and CHMP4A in epidermal than in normal skin." (PMID 37620327, 2023). "Histologically, melanoma tissues had fewer positive cells percentage of pyroptosis-related genes (PRGs), GZMA, GSDMB, NLRP1, IL18, and CHMP4A in epidermal than in normal skin." (PMID 37620327, 2023). "The initial findings from the enzyme-linked immunosorbent assay (ELISA) indicated a statistically significant downregulation of pyroptosis protein expression in melanoma patients when compared to the control group, especially NLRP1, GZMA, and GSDMB, followed by CHMP4A and IL18." (PMID 37620327, 2023). "Although the clinical evidence implied that melanoma skin tissue reduced GZMA, GSDMB, NLRP1, IL18, and CHMP4A expression in epidermal, however, the result obtained with bulk-sorted samples could not explain the main scientific questions on cell sources heterogeneity." (PMID 37620327, 2023).
cataract (1 paper, 2023). Partial or complete opacity of the crystalline lens of one or both eyes that decreases visual acuity and eventually results in blindness. "In addition, the GeneCards database associates CHMP4A with cataract 32, which includes early onset lamellar cataracts, the phenotype presented by our proband." (PMID 37511188, 2023). "However, knowing the importance of protein and metabolic degradation in the lens, it would be expected that an alteration in the CHMP4A pathway would lead to lens opacities, thus classifying this gene as a possible causative gene for pediatric cataracts." (PMID 37511188, 2023).
liver cancer (1 paper, 2022). An epithelial or non-epithelial malignant neoplasm that arises from the liver. "The expression of CHMP4A, SCAF11, and GSDMC was high in liver cancer tissue." (PMID 35309514, 2022).
tumor (7 papers, 2020 to 2025). "In endothelial cells, the upregulation of genes related to pyroptosis, mainly dominated by CHMP4A, activates several pathways, for example, tumor-associated necrosis factor, induces angiogenesis, wound healing and so on, to promote tumor formation and metastasis." (PMID 39744500, 2025). "Accumulating evidence has shown that hypoxia is a common phenomenon in the growth of solid tumor, and CHMP4A acts as the modulator to increase the expression level of hypoxia-inducible factor-1 α protein (HIF-1α), promoting the tumor progression in a hypoxia-associated pro-tumor mechanism." (PMID 36267972, 2022). "In parallel, RT-qPCR detection demonstrated the transcription levels of CHMP4A, HMGB1 and PLK1 were increased in tumor tissues compared to normal ones." (PMID 36267972, 2022). "Moreover, the protein levels of these three genes were detected using the human protein atlas (HPA) database, and the result showed the significant higher expression of CHMP4A, HMGB1 and PLK1 in the tumor tissues than in the normal ones." (PMID 36267972, 2022).
cancer (4 papers, 2020 to 2022). A tumor composed of atypical neoplastic, often pleomorphic cells that invade other tissues. "We furthermore discovered 5 genes (MDGA1, VEGFC, MCM10, CTBP1-DT, CHMP4A) with three OS correlations, and 22 genes with two OS correlations, across eight cancer types." (PMID 32764426, 2020). "Of these, low expressions of CTBP1-DT and CHMP4A correlated with poor OS, making them possible candidates for acidosis-stimulated cancer aggressiveness." (PMID 32764426, 2020).
CHMP4A also shares sentences with these, for which no sentence is quoted: infection (4 papers); colorectal cancer (2); hepatocellular carcinoma (2); COVID-19 (1); glioma (1); preeclampsia (1); Sepsis (1).